NDUFA13 (NADH:ubiquinone oxidoreductase subunit A13)
Diseases named in the same sentence as NDUFA13 in open-access papers:
NDUFA13 is named in the same sentence as 85 diseases in open-access papers, as found by Europe PMC text mining. Sharing a sentence is not in itself a finding about the gene and the disease. The quoted sentences say what the papers report.
breast carcinoma (11 papers, 2013 to 2024). "NDUFA13 expression serves as a positive biomarker for the activation of the ferroptosis pathway in breast cancer patients." (PMID 39867656, 2024). "Our study showed that the overexpression of NDUFA13 was correlated with a significant increase in the DMFS of breast cancer patients (mRNA: P < 0.001, Protein: P = 0.085)." (PMID 36119477, 2022). "Firstly, expression analysis revealed over-expression of NDUFA13 in breast cancer and several other cancers, indicating putative oncogenic functions of NDUFA13 in tumors." (PMID 36119477, 2022). "The hypermethylation of the NDUFA13 promoter leads to the downregulation of the gene, which increases cell proliferation and subsequently leads to the onset of breast cancer." (PMID 37529293, 2022). "NDUFA13 expression was identified as a positive biomarker for ferroptosis pathway activation in breast cancer patients." (PMID 36119477, 2022). "Gene associated with retinoid-interferon-induced mortality-19 (GRIM-19, also known as NDUFA13) was initially identified as a novel cell death-regulatory molecule in a breast carcinoma cell line by the antisense knockout technique." (PMID 29074558, 2017). "In particular, ferroptosis pathway status was significantly associated with clinical outcomes and intra-tumoral heterogeneity in breast cancer patients, as NDUFA13 expression was identified as a positive biomarker for activating the ferroptosis pathway in breast cancer patients." (PMID 39867656, 2024). "In conclusion, the status of the ferroptosis pathway significantly correlated with the clinical outcomes and intra-tumor heterogeneity of breast cancer, and NDUFA13 expression was identified as a positive biomarker for ferroptosis pathway activation in breast cancer patients." (PMID 36119477, 2022). "Indeed, NDUFA13 has been found downregulated in different tumors including hepatocellular, cervical, colorectal, renal cell carcinoma, and breast cancer compared to their respective normal tissues." (PMID 29735924, 2018). "We employ bioinformatics analyses of breast cancer cell line MCF7 to derive our model system, based on the promoter of the NDUFA13 gene." (PMID 37529293, 2022). "Using NGS data on breast cancer cell line MCF7, we have investigated the mechanistic impact of abnormal DNA methylation in the non-coding genome on the downregulation of the NDUFA13 gene." (PMID 37529293, 2022). "We identify in the breast cancer cell line MCF7, a hypermethylated region within the promoter of the NDUFA13 gene, 130 b.p." (PMID 37529293, 2022).
prostate carcinoma (8 papers, 2015 to 2023). A carcinoma that arises from epithelial cells of the prostate gland. "As a result, the high expression of the USP34 has a protective effect on prostate cancer recurrence in TCGA and GEO gene expression profile, and the gene NDUFA13, UQCR11 is the opposite." (PMID 31795990, 2019). "NDUFA13 inhibits cell growth of prostate cancer by regulating the expression of miR-423-5p." (PMID 31795990, 2019). "We finally screened three genes related to prostate cancer recurrence: NDUFA13, UQCR11, USP34." (PMID 31795990, 2019). "So, further we expect that Low-dose lymphocyte immunotherapy might be an effective therapy for prostate cancer, and even NDUFA13, UQCR11, and USP34 might be immunocheckpoints like PD-1/ PD-L1, they may play its role through Th2 and Tcm cells." (PMID 31795990, 2019).
autoimmune disease (4 papers, 2016 to 2025). A disorder resulting from loss of function or tissue destruction of an organ or multiple organs, arising from humoral or cellular immune responses of the individual to their own tissue constituents. "The non-CHD indications of clinically used drugs included dyslipidemias (PPARA), type 2 diabetes (PPARG and NDUFA13), autoimmune diseases (TNF), neoplasms (RAF1 and PSMA5), circulatory disorders (ABCA1, PLG, ITGB3, and F2), and alcohol-dependency (ALDH2)." (PMID 34675202, 2021).
Leigh syndrome (4 papers, 2020 to 2025). "Consideration of the clinical features of all patients now reported with NDUFA13 variants revealed early faltering growth in 9/13 cases, a frequent feature in Leigh syndrome of many causes." (PMID 39816196, 2025). "In conclusion, our results support the dual diagnosis of PGM1-CDG and Leigh syndrome caused by NDUFA13 deficiency." (PMID 40358162, 2025). "Proband’s clinical characteristics and their overlap with PGM1-CDG or NDUFA13/Leigh syndrome patients." (PMID 40358162, 2025). "Here, we present the first case with dual diagnosis of CDG and Leigh syndrome caused by (likely) pathogenic variants in PGM1 and NDUFA13." (PMID 40358162, 2025). "Imaging of one Leigh syndrome cohort demonstrated substantia nigra lesions in 60%,10 while a neuropathological review revealed substantia nigra lesions in 95% of cases, suggesting that substantia nigra involvement is not specific for NDUFA13 disease." (PMID 39816196, 2025).
thyroid cancer (4 papers, 2013 to 2021). "Benign and malignant thyroid tumors with an oncocytic phenotype have been associated with germline and somatic mutations in the NDUFA13/GRIM-19 (19p13.11) gene." (PMID 33495912, 2021). "Mutations in TIMM44 and NDUFA13 have been reported to be associated with tumorigenesis in the thyroid, and the SLC5A5 gene encodes sodium-iodide symporter protein, whose down-regulation is associated with thyroid carcinomas." (PMID 23724128, 2013).
papillary carcinoma (3 papers, 2005 to 2021). A malignant epithelial neoplasm characterized by a papillary growth pattern. "Mutations of the gene NDUFA13 (also known as GRIM 19) have been identified in oncocytic thyroid tumors.In one study, somatic missense mutations in NDUFA13 were found in 10–20% of oncocytic follicular carcinoma and the oncocytic variant of papillary carcinoma." (PMID 24868250, 2013).
asthma (2 papers, 2020 to 2021). "In addition to these four apoptosis-related genes (TRIO, PEA15, KLRK1, NDUFA13), we also found that the other genes in desensitization-treatment-related module exhibiting distinct degree of correlations to asthma via literature review." (PMID 32948203, 2020).
Ataxia (2 papers, 2016 to 2025). Ataxia refers to impaired coordination of voluntary muscle movement. "It is interesting that NDUFA13 deficiency in synapses correlates well with ataxia which suggests that synaptic pathology could contribute to mitochondrial disease pathogenesis in these patients." (PMID 26337858, 2016). "Analysis of NMDAS scores and NDUFA13 expression in synapses reveals a statistically significant relationship between higher NMDAS scores, indicating a more severe ataxia, and lower z scores, indicating more complex I deficiency (Spearman's rho = −0.60, P value = 0.0493)." (PMID 26337858, 2016).
developmental delay (2 papers, 2025). "On the one hand, the clinical presentation consistent with NDUFA13 deficiency in our patient included global developmental delay, seizures, dystrophy, hearing loss, a Leigh-like MRI pattern and high lactate levels in blood and CSF." (PMID 40358162, 2025). "Individuals with the LOF NDUFA13 variants exhibited isolated motor delay with preserved cognitive function, whereas all homozygous carriers of the recurrent NDUFA13 c.170G > A, p.(Arg57His) variant were cognitively impaired as part of their global developmental delay." (PMID 39963288, 2025).
glioma (2 papers, 2017 to 2021). A benign or malignant brain and spinal cord tumor that arises from glial cells (astrocytes, oligodendrocytes, ependymal cells). "In addition, we found that four of the candidate tumor gene biomarkers (NDUFS5, NDUFA1, NDUFA13, and NDUFB8) belong to the NADH ubiquinone oxidoreductase subunit gene family, so we inferred that this gene family may be strongly related to glioma." (PMID 34863158, 2021).
Huntington disease (2 papers, 2016 to 2021). Huntington disease (HD) is a rare neurodegenerative disorder of the central nervous system characterized by unwanted choreatic movements, behavioral and psychiatric disturbances and dementia. "The two subunits of mitochondrial complex I NDUFB7 and NDUFA13 are associated with Alzheimer’s, Parkinson’s and Huntington’s diseases." (PMID 27314336, 2016).
hypertrophic cardiomyopathy (2 papers, 2020 to 2025). A condition in which the myocardium is hypertrophied without an obvious cause. "Our patient, who represents the second family report with mutations in the CI NDUFA13 subunit, presented with LS lesions in brain magnetic resonance imaging, mild hypertrophic cardiomyopathy, and progressive spastic tetraparesis." (PMID 32722639, 2020).
cardiomyopathy (1 paper, 2023). A disease of the heart muscle or myocardium proper. "Three out of the 34 OXPHOS genes that did not demonstrate cardiomyopathy in humans did demonstrate cardiomyopathy in mice (Ndufa13, Bcs1l, Aifm1)." (PMID 37103033, 2023).
congenital glaucoma (1 paper, 2025). "The sole limb malformation and skeletal dysplasia and congenital glaucoma phenotype in a patient with the homozygous NDUFA13 c.187G > A, p.(Glu63Lys) variant could suggest that this variant is most probably hypomorphic." (PMID 39963288, 2025). "Interestingly, the NDUFA13 c.187G > A, p.(Glu63Lys) variant identified in Family 9 in a heterozygous state was also found in a patient with limb malformation and skeletal dysplasia and congenital glaucoma, but in a homozygous state (Individual 14, Family 12)." (PMID 39963288, 2025).
COVID-19 (1 paper, 2023). A disease caused by infection with severe acute respiratory syndrome coronavirus 2. "However, under reduced oxygen saturation in the lung of COVID-19 patients, downregulation of genes encoding lipid uptake, FAO, and NADH oxidation (NDUFB8, NDUFA11, NDUFA13) was found in severe COVID(+) NKTs suggesting mitochondrial dysfunction in NKTs during SARS-CoV-2 infection." (PMID 37029220, 2023).
myocardial ischemia (1 paper, 2023). A disorder of cardiac function caused by insufficient blood flow to the muscle tissue of the heart. "NDUFA13 encodes a subunit of mitochondrial complex I, and its downregulation creates a leak within complex I, which significantly suppresses the superoxide burst and eventually dampens myocardial ischemia and reperfusion injury." (PMID 36782329, 2023).
oncocytic adenoma (1 paper, 2025). A benign neoplasm composed of large cells with abundant eosinophilic granular cytoplasm. "Oncocytic adenomas often exhibit mitochondrial DNA mutations that impair oxidative phosphorylation, and a significant proportion show copy number alterations or mutations in mitochondrial complex I‐related gene (e.g., GRIM19/NDUFA13)." (PMID 41164799, 2025).
prostate tumors (1 paper, 2025). "Immunohistochemical analysis further confirmed lower expression levels of representative proteins such as Ndufa13 and Ndufs8 in prostate tumors derived from Lonp1KI mice and Pten−/−; Lonp1KI mice when compared to those from the control group." (PMID 39971909, 2025).
tumor (38 papers, 2005 to 2024). "In particular, the CI accessory subunit NDUFA13, also known as Gene associated with Retinoic-Interferon-induced Mortality 19 (GRIM-19), has been widely investigated for its role in tumor progression and metastasis formation." (PMID 29735924, 2018). "The NDUFA13 gene encodes a NADH dehydrogenase enzyme, a part of the electron transport chain in mitochondria that can function as a tumour suppressor (Pinto and Máximo, 2018)." (PMID 37529293, 2022). "Down-regulation of the NDUFA13 gene in the pathways has been shown to correlate with lymph node metastasis and advanced tumour-node-metastasis (TNM) stage in breast cancer." (PMID 32978398, 2020). "It is known that NDUFA13 subunit is the first one to be reprogrammed from the oxidative metabolism to glycolysis during tumor progression." (PMID 30581847, 2018). "NDUFA13 has been found to act as a tumor suppressor by keeping STAT3 in its inactive state and preventing oncogenic transformation, cell survival and proliferation, migration, and EMT." (PMID 29735924, 2018). "NDUFA13 may affect energy metabolism in tumor cells, particularly adapting to mitochondrial dysfunction and oxidative stress." (PMID 39726602, 2024). "The complex I catalyzes the electron transfer from NADH to ubiquinone in the first step of the mitochondrial respiratory chain, and its subunit NDUFA13, in addition to be required for electron transfer, functions as a tumor suppressor that binds to STAT3 and inhibits its transcriptional activity." (PMID 35359604, 2022). "It has been reported that down-regulated NDUFA13 rendered tumor cells more resistant to apoptosis." (PMID 31795990, 2019). "For example, it is reported that the expression level of NDUFA13, a subunit of mitochondrial respiratory chain complex I, decreases in a variety of tumors, such as lung, gastric, and liver tumors, which promotes tumorigenesis by inhibiting tumor cell apoptosis." (PMID 33937399, 2021). "Through WGCNA and Lasso, we identified that NDUFA13, UQCR11, and USP34 involved in the infiltration of Th2 cells and Tcm in tumor tissues, and the expression of genes is related to the recurrence of patients." (PMID 31795990, 2019). "Further, the expression of NDUFB7, AURKAIP1, ROMO1, SCAND1, GADD45GIP1, and NDUFA13 was upregulated in the four tumor subtypes compared with normal adjacent tissue." (PMID 34996995, 2022). "In addition, we found that four (NDUFS5, NDUFA1, NDUFA13, and NDUFB8) of the candidate tumor gene biomarkers belong to the NADH ubiquinone oxidoreductase subunit gene family." (PMID 34863158, 2021). "Moreover, the high expression of the gene NDUFA13 and UQCR11 may inhibit the body’s immune system from recognizing tumors, and the probability of tumor recurrence will be significantly improved." (PMID 31795990, 2019). "In fact, of all protein subunits with significant differences in abundance between tumor and nontumor, only 4 were significantly upregulated in DEN-T: Ndufa13, Ndufs3, Ndufs8, and Ndufv2." (PMID 35756609, 2022).
cancer (20 papers, 2011 to 2025). A tumor composed of atypical neoplastic, often pleomorphic cells that invade other tissues. "Here, we investigate a molecular mechanism driving the downregulation of the NDUFA13 gene, due to hypermethylation, which is associated with multiple cancers." (PMID 37529293, 2022). "It was suggested that downregulation of NDUFA13, which is a subunit of mitochondrial complex I, reduces ROS production and promotes resistance of cancer cells to apoptosis." (PMID 40422535, 2025). "We see our results as a starting point for further experimental validation that will or will not show that the ability of CEBPB and E2F1-DP1 TF dimers to cooperatively bind to DNA upon methylation affects the NDUFA13 gene transcription and, potentially, lead to the onset of cancers." (PMID 37529293, 2022). "Whereas the precise functions of NDUFA3, NDUFA13 (also called GRIM19), COX7A1, COX4I2 and ATP5F1D in oxidative phosphorylation remain somewhat poorly understood, increased expression of NDUFA4L2 is known to drive pro-oncogenic phenotypes in numerous cancer types." (PMID 34782604, 2021).
neurodegenerative disease (1 paper, 2024). A disorder of the central nervous system characterized by gradual and progressive loss of neural tissue and neurologic function. "GO and KEGG analyses of ME7 also identified upregulation of genes related to mitochondrial oxidative phosphorylation, including NDUFS6, NDUFA13, NDUFB7, NDUFA3, and NDUFS5, which are involved in a variety of neurodegenerative diseases." (PMID 37971544, 2024).
NDUFA13 also shares sentences with these, for which no sentence is quoted: cervical cancer (4 papers); gastric cancer (4); hepatocellular carcinoma (4); renal cell carcinoma (4); adenomyosis (3); colorectal cancer (3); diabetes (3); infection (3); Obesity (3); Alzheimer disease (2); inflammatory bowel disease (2); lung adenocarcinoma (2); lung carcinoma (2); mitochondrial disease (2); multiple sclerosis (2); oncocytic tumors (2); oral squamous cell carcinoma (2); osteosarcoma (2); Parkinson’s (2); skeletal dysplasia (2); thyroid (2); thyroid tumor (2); acute graft versus host disease (1); asthenozoospermia (1); bacterial infections (1); basal cell carcinoma (1); bladder cancer (1); breast (1); Cerebellar atrophy (1); cervical tumors (1).
A further 34 diseases each share a sentence with NDUFA13 in 1 paper.